MIR574 (microRNA 574)
Synonyms: hsa-mir-574; MIR574-3p; MIRN574; mir-574
Gene: MicroRNA gene on chromosome 4 (38,868,032 to 38,868,127, forward strand). Ensembl gene ENSG00000207944.
Gene Ontology:
Biological process: miRNA-mediated post-transcriptional gene silencing
Diseases named in the same sentence as MIR574 in open-access papers:
MIR574 is named in the same sentence as 2 diseases in open-access papers, as found by Europe PMC text mining. Sharing a sentence is not in itself a finding about the gene and the disease. The quoted sentences say what the papers report.
glioblastoma (1 paper, 2021). The most malignant astrocytic tumor (WHO grade IV). "We found previously uncharacterized miRNA genes in pediatric CNS tumors, including MIR149, MIR214, MIR574 and MIR765, apart from one study that reported MIR595 upregulation in glioblastoma compared to control cells, in vitro." (PMID 34204289, 2021).
CNS tumors (1 paper, 2021). "In cluster 2, MIR149, MIR214, MIR574, MIR595 and MIR765 were globally down-regulated across all CNS tumor samples; ten miRNA genes were also found globally down-regulated in >90% of all samples." (PMID 34204289, 2021).